SPATA16 (spermatogenesis associated 16)
Description:
Essential for spermiogenesis and male fertility (By similarity). Involved in the formation of sperm acrosome during spermatogenesis.
Synonyms: NYD-SP12; SPGF6
Tractability: PROTAC: ubiquitination databases record sites on it.
Gene: Protein-coding gene on chromosome 3 (172,889,357 to 173,141,235, reverse strand). Ensembl gene ENSG00000144962.
Subcellular location: Golgi apparatus; Cytoplasmic vesicle, secretory vesicle, acrosome
Gene Ontology:
Biological process: spermatid development; spermatogenesis
Cellular component: Golgi apparatus; acrosomal vesicle
Genetic constraint (gnomAD): Loss-of-function variants: 35 observed, 61.18 expected, observed/expected ratio (o/e) 0.57, 90% interval 0.44 to 0.76. The upper end of that interval is the gene's LOEUF score, 0.76, which puts it in group 3 of 6, group 1 being the genes least tolerant of losing a copy. Missense variants: 639 observed, 707.84 expected, observed/expected ratio (o/e) 0.9, 90% interval 0.85 to 0.96. Synonymous variants: 200 observed, 228.55 expected, observed/expected ratio (o/e) 0.88, 90% interval 0.78 to 0.98.
Homologues: Orthologues: macaque SPATA16 (96% identical), chimpanzee SPATA16 (89% identical), pig SPATA16 (86% identical), rabbit SPATA16 (85% identical), dog SPATA16 (83% identical), guinea pig SPATA16 (82% identical), mouse Spata16 (79% identical), rat Spata16 (76% identical), Caenorhabditis elegans unc-45 (9% identical), Drosophila melanogaster unc-45 (9% identical), Drosophila melanogaster Sgt (7% identical). Paralogues in human: UNC45B (13% identical), SPAG1 (13% identical), RPAP3 (12% identical), UNC45A (12% identical), TTC12 (11% identical), ST13 (10% identical), TTC4 (10% identical), SGTA (9% identical), SGTB (9% identical), STUB1 (9% identical), TTC1 (9% identical), SUGT1 (9% identical), and 6 more.
Diseases named in the same sentence as SPATA16 in open-access papers:
SPATA16 is named in the same sentence as 13 diseases in open-access papers, as found by Europe PMC text mining. Sharing a sentence is not in itself a finding about the gene and the disease. The quoted sentences say what the papers report.
Globozoospermia (21 papers, 2016 to 2025). Any structural anomaly of the acrosome resulting in a round sperm head. "Dysfunction of the SPATA16 protein results in male infertility caused by oligoasthenoteratozoospermia, total globozoospermia." (PMID 39045326, 2024). "SPATA16 was first identified in 2007 as being mutated in three brothers affected with globozoospermia." (PMID 38790229, 2024). "In partial globozoospermia, mutations were found in the DPY19L2 and SPATA16 genes affected in patients with ‘classic’ globozoospermia." (PMID 39045326, 2024). "Patient 12 with partial globozoospermia also had decreased sperm count and low motility, most likely due to a homo/hemizygous variant of the nucleotide sequence in the SPATA16 gene." (PMID 39045326, 2024). "Subsequent studies have confirmed that Spata16 is closely associated with acrosome formation and that its pathogenic mutations can cause globozoospermia and male infertility." (PMID 35741761, 2022). "The spermatogenesis associated (SPATA16) gene is encodes a protein located in Golgi apparatus and pro-acrosomic vesicles which is associated with globozoospermia." (PMID 35248021, 2022). "Recently, studies have suggested that SPATA16 gene is involved in sperm production and can cause to globozoospermia, testicular diseases, spermatogenesis arrest, and sperm aneuploidy in human." (PMID 35248021, 2022). "Similar to Spata16 and Pick1, Dpy19l2 is the third gene in which defects have been identified to be closely associated with globozoospermia." (PMID 35741761, 2022). "Analyzing the reported percentage of DPY19L2 mutations, together with those of the two other globozoospermia-associated genes SPATA16 and PICK1, more than half of the cases carried DPY19L2 mutations, with a rather lower frequency of SPATA16 or PICK1 mutations." (PMID 34209343, 2021). "Although pathogenic variants in DPY19L2 and SPATA16 are known causes of globozoospermia and explain up to 70% of all cases, genetic causality remains unexplained in the remaining patients." (PMID 31985809, 2020). "The causes of globozoospermia are genetic and, as far as we are currently aware, involve mutations in three genes, SPATA16 (spermatogenesis associated 16), PICK1 (protein interacting with PRKCA 1) and DPY19L2 (DPY-19 like 2) with the latter being dominant." (PMID 33101214, 2020). "In conclusion, according to the evidence reported so far, besides DPY19L2, other genes that might be confidently associated with globozoospermia in humans, and whose analysis might be recommended in clinical practice, are SPATA16, PICK1, ZPBP1, and CCDC62." (PMID 38790229, 2024). "Therefore, the aim of our study was to investigate the genetic contribution of the main globozoospermia-associated genes (SPATA16, PICK1 and DPY19L2) in 18 unrelated Italian men." (PMID 34209343, 2021). "After pre-screening 16 men for mutations in known globozoospermia genes DPY19L2 and SPATA16, exome sequencing was performed in 15 males with globozoospermia or acrosomal hypoplasia of unknown aetiology." (PMID 31985809, 2020). "Mutations or deletions in SPATA16 have been shown to be responsible for globozoospermia." (PMID 31333723, 2019). "Also genes in which mutations may lead to infertility, such as DPY19L2 or SPATA16, were proved to be associated with male infertility in human globozoospermia studies." (PMID 31671693, 2019). "Human genes thathave been largely associated with globozoospermia include proteins interactingwith C kinase 1 (PICK1), SPATA16, zonapellucida binding protein 1 (ZPBP1), and Dpy-19-like-2(DPY19L2)." (PMID 40833973, 2025). "To date, several genes (most commonly DPY19L2, SPATA16) have been described in patients with isolated globozoospermia or globozoospermia combined with oligozoospermia." (PMID 39045326, 2024). "Genetic defects in the DPY19L2 and SPATA16 genes have been identified in patients with partial globozoospermia, although the number of spherical spermatozoa is less than 50%." (PMID 39045326, 2024).
Globozoospermia (continued). "Genetic defects in the DPY19L2 and SPATA16 genes have been identified in our patients with partial globozoospermia, although the number of spherical spermatozoa is less than 50%." (PMID 39045326, 2024). "The most common abnormality is variation in the DPY19L2 gene, while variations in the SPATA16, PICK1 and GGN have also been investigated as causes of globozoospermia." (PMID 34361119, 2021). "In particular, recessive deletions and point mutations of three genes, dpy-19-like 2 (DPY19L2), spermatogenesis associated 16 (SPATA16) and protein interacting with C Kinase (PICK 1) result in globozoospermia phenotype." (PMID 33155089, 2021). "Our genetic analysis of 3 CG men confirmed a deletion of 3 genes—DPY19L2, SPATA16, and PICK1—which are often associated with the globozoospermia phenotype and contribute to the most relevant feature of this condition, the absence of acrosome." (PMID 33877510, 2021). "Of interest, ZPBP forms part of the same gene interaction network with known globozoospermia genes SPATA16 and DPY19L2, thus suggesting they are mechanistically linked." (PMID 31985809, 2020). "A subset of genetic mutations, such as DNAH6, SPATA16, DPY19L2, PICK1, and CCIN related to globozoospermia, have been reported in the past few years." (PMID 32582379, 2020). "SPATA16 was the first gene which was shown to contribute to human globozoospermia with an autosomal dominant pattern of inheritance." (PMID 30291685, 2019). "Next, the onset of Spata16 expression was examined by RT-PCR and compared with that of globozoospermia-related genes: Dpy19l2, Pick1, and Spaca1." (PMID 29065458, 2017). "Regarding the other genes, in the present study mutation screening of the SPATA16 and PICK1 genes were also carried out on 27 cases with globozoospermia and 30 fertile men." (PMID 27441053, 2016). "Researchers have recently identified a large deletion, about 200 kbp,encompassing the whole length of DPY19L2 or mutations in SPATA16 and PICK1 genesassociated with globozoospermia." (PMID 27441053, 2016). "Three infertile patients (one man with complete globozoospermia and two ones with partial globozoospermia) underwent whole exome sequencing (WES), which revealed nucleotide sequence variants in the DPY19L2 and SPATA16 genes that relevant to globozoospermic phenotype." (PMID 39045326, 2024). "While this evidence points towards a SPATA16 protein role in acrosome formation, mutant mice with the corresponding aminoacidic substitution in Spata16 did not appear to be associated with globozoospermia, as reported in a recent study." (PMID 34209343, 2021). "However, Spata16-KO demonstrated a lackof spermiogenesis instead of globozoospermia." (PMID 40833973, 2025). "The genetic defects in the DPY19L2 and SPATA16 genes detected in patients from both globozoospermic groups suggest a generalized disruption of nuclear structure in globozoospermia, highlighting the genetic and phenotypic similarities between complete and partial globozoospermia." (PMID 39045326, 2024). "Pathogenic variants of the nucleotide sequence in the SPATA16 gene in homozygous and compound heterozygous states have been described in patients with spermatogenesis disorder, type 6 (SPGF6), associated with oligoasthenoteratozoospermia, globozoospermia (OMIM 102530)." (PMID 39045326, 2024). "However, the genetic assessment failed to include additional genes associated with globozoospermia, such as SPATA16 and PICK1." (PMID 33877510, 2021). "We found that the point mutation in Spata16 was not essential for male fertility; however, deletion of the fourth exon of Spata16 resulted in infertile male mice due to spermiogenic arrest but not globozoospermia." (PMID 29065458, 2017). "Only, four genes have been so far detected in individuals presenting globozoospermia including DPY19L2, SPATA16, PICK1 and Calicin." (PMID 30291685, 2019).
Globozoospermia (continued). "Globozoospermia is a rare male infertility disorder in which spermatozoa have round heads, abnormal or absent acrosomes, and are often defective in two genes, DPY19L2 and SPATA16." (PMID 38279344, 2024). "As mice carrying the deletion experienced normal acrosome biogenesis, the authors assumed that mouse Spata16 is not related to globozoospermia." (PMID 34209343, 2021). "Because the amount of testicular SPACA1 only slightly reduced in Spata16−781/−781 mice, we can assume that mouse SPATA16 is not related to globozoospermia." (PMID 29065458, 2017).
male infertility (12 papers, 2012 to 2025). The inability of the male to effect fertilization of an ovum after a specified period of unprotected intercourse. "For example, although Spata16 knock-out causes infertility in male mice, mice with a knock-in of a variant that segregated with male infertility in a pedigree with three affected individuals retained fertility." (PMID 38540391, 2024). "This region overlaps with the protein-coding gene SPATA16, which is associated with spermatogenesis and male infertility." (PMID 27142071, 2016). "Deletion of the fourth exon of mouse Spata16 caused male infertility with a spermiogenic arrest." (PMID 29065458, 2017). "The SPATA16, CFTR, KIF6, STPG2, and DRC7 mutations are associated with male infertility, specifically azoospermia, and a further examination of this genetic function is required." (PMID 37895049, 2023). "Several genetic mutations, including PRM1, AURKC, SPATA16, PICK1, DPY19L2, SEPT12, and SEPT14, result in male infertility and are caused by sperm DNA damage in a clinical context." (PMID 36295569, 2022). "In this study, an Ampiseq targeted NGS panel and Illumina TruSeq WES were both used to pinpoint six specific genes (KIF6, DRC7, STPG2, SPATA16, CFTR, CMTM2) that play a role in MT association and spermiogenesis, which are crucial factors in understanding the causes of male infertility." (PMID 37895049, 2023). "SPATA16, previously named NYD-SP12, is one of the causative agents of male infertility." (PMID 35737328, 2022). "In general, our study provided a more understanding of male infertility as a heterogeneous disorder, and suggested that CATSPER1 (rs2845570) and SPATA16 (rs1515442) genes polymorphism are significantly associated with the risk of idiopathic azoospermia and oligospermia in Iranian Azeri population." (PMID 35248021, 2022). "SPATA16 has been associated with male infertility, but has no known relationship to arthritis or autoimmune disease." (PMID 23148518, 2012).
Infertility (5 papers, 2017 to 2024). "In contrast, the Spata16−781/−781 males were infertile due to spermiogenic arrest, despite 781-bp deletion causing an in-frame mutation of Spata16 by mis-translation of the fourth exon." (PMID 29065458, 2017). "Recent genetic studies of infertility patients identified causative mutations in three genes: a protein interacting with C kinase 1 (PICK1), dpy 19-like 2 (DPY19L2), and spermatogenesis associated 16 (SPATA16)." (PMID 29065458, 2017). "First, all 16 patients were pre-screened for deletions and/or mutations in DPY19L2 and SPATA16, using a combination of targeted next-generation sequencing (NGS) and Sanger sequencing to detect point mutations and CNVs in these two genes and other known infertility genes." (PMID 31985809, 2020). "These genes play important roles in cell proliferation (RFX4, FOXM1, ASF1B), differentiation during spermatogenesis (CATSPERG, SPDYA, SPATA16, TSACC, TCP10L, DPY19L2) and motility of sperm cells during fertilization (DNAAF1); mutations in these genes may lead to infertility." (PMID 31671693, 2019).
Azoospermia (2 papers, 2022 to 2023). Absence of any measurable level of sperm,whereby spermatozoa cannot be observed even after centrifugation of the semen pellet. "The aim of this study was to investigate association of idiopathic azoospermia and oligospermia with single-nucleotide polymorphisms of CATSPER1, SPATA16 and TEX11 genes in Iranian-Azeri men." (PMID 35248021, 2022). "Miscellaneous variants in CATSPER1, SPATA16, and TEX11 genes are identified that play important roles in pathogenesis of sperm morphology (teratozoospermia), sperm motility parameters (asthenozoospermia), or sperm number (oligozoospermia or azoospermia) in human." (PMID 35248021, 2022). "Notably, our findings provide further support for mutations in SPATA16 and CFTR genes being associated with non-obstructive oligozoospermia and azoospermia with normal morphology." (PMID 37895049, 2023).
teratozoospermia (1 paper, 2021). "It should be stressed that the lack of genetic variants of SPATA16 and PICK1 we observed could be due to the small caseload caused by the rarity of this monomorphic teratozoospermia." (PMID 34209343, 2021).
SPATA16 also shares sentences with these, for which no sentence is quoted: Arthritis (1 paper); autoimmune disease (1); macrozoospermia (1); metastatic melanoma (1); metastatic tumors (1); oligoasthenoteratozoospermia (1); oligospermia (1); testicular diseases (1).